FETUB (fetuin B)
Diseases named in the same sentence as FETUB in open-access papers (continued):
Sharing a sentence is not in itself a finding about the gene and the disease.
Hyperinsulinemia (4 papers, 2020 to 2022). An increased concentration of insulin in the blood. "Given the independent association of high Fetuin-B levels with low insulin-mediated suppression of adipose tissue lipolysis it is tempting to speculate, that Fetuin-B might represent a crucial element diminishing antilipolytic effects of insulin, e.g., during postprandial hyperinsulinemia." (PMID 34611132, 2021). "Most interestingly, basal Fetuin-B level were related to short- and long-term improvement of adipose insulin sensitivity inhibiting lipid breakdown during hyperinsulinemia." (PMID 34611132, 2021). "In response to hyperinsulinemia, serum fetuin-B levels significantly increased in patients with MetS, whereas there was no change in healthy subjects." (PMID 34646426, 2021). "We believe that an increase in serum fetuin-B levels in patients with MetS can be attributed to elevated metabolic stress, involving, for example, hyperinsulinemia, dyslipidosis, and antioxidative disorder." (PMID 34646426, 2021). "The results from the OGTT suggest that in healthy women, hyperglycemia and/or hyperinsulinemia can stimulate the secretion and release of Fetuin-B in vivo." (PMID 33061822, 2020). "To investigate the impact of hyperglycemia or/and hyperinsulinemia on serum Fetuin-B levels in vivo, we performed an OGTT test in both PCOS and healthy women." (PMID 33061822, 2020). "Using multiple interventions, we showed that Fetuin-B levels in healthy women were affected by blood glucose levels, while in IR state, circulating Fetuin-B was affected by hyperinsulinemia." (PMID 33061822, 2020). "To answer this question, we conducted an OGTT (both hyperglycemia and hyperinsulinemia) to study the impacts of nutritional status and hormone (insulin) on serum Fetuin-B in vivo." (PMID 33061822, 2020). "Therefore, it is possible that chronic hyperinsulinemia related to IR results in an increase in fetuin-B levels." (PMID 34646426, 2021). "Therefore, blood glucose was the main factor affecting circulating Fetuin-B in healthy women, while in women with PCOS, hyperinsulinemia and IR were the main factors to determine circulating Fetuin-B levels." (PMID 33061822, 2020). "During EHC, under the conditions of hyperinsulinemia and euglycemia, serum fetuin-B levels did not change in healthy subjects; however, a significant increase in serum fetuin-B levels was observed in patients with MetS." (PMID 34646426, 2021). "This state allowed us to observe the regulation of Fetuin-B by hyperinsulinemia without being affected by blood glucose." (PMID 33061822, 2020). "Surprisingly, hyperinsulinemia led to a marked increase in circulating Fetuin-B levels in PCOS subjects, but not in control women." (PMID 33061822, 2020). "Therefore, we believe that hyperglycemia, not hyperinsulinemia, is the main factor affecting serum fetuin-B levels in healthy individuals." (PMID 34646426, 2021). "Therefore, serum fetuin-B levels did not change during OGTTs under the conditions of hyperglycemia and hyperinsulinemia." (PMID 34646426, 2021).
Hypertension (4 papers, 2021 to 2025). The presence of chronic increased pressure in the systemic arterial system. "A restricted spline curve showed that the incidence of hypertension increased with increases in serum fetuin-B, and serum fetuin-B was a risk factor of hypertension." (PMID 37811770, 2023). "Serum fetuin-B was still an independent risk factor for hypertension after adjusting for anthropometric variables including gender, blood lipid levels, FBG, and other factors." (PMID 37811770, 2023). "Fetuin-B plays an important role in regulating lipid metabolism and can result in lipid abnormalities that increase the risk of hypertension, cardiovascular disease, and endothelial dysfunction." (PMID 37811770, 2023). "Logistic regression analysis suggested that serum fetuin-B was an independent risk factor for essential hypertension." (PMID 37811770, 2023). "Our study found that fetuin-B is associated with the occurrence and development of hypertension." (PMID 37811770, 2023). "Therefore, to avoid these shortcomings, we investigated the association of fetuin-B with hypertension in newly diagnosed hypertensive patients." (PMID 37811770, 2023). "Elevated fetuin-B levels are associated with an increased risk of essential hypertension." (PMID 37811770, 2023). "While this study did not allow us to deduce the causal relationship between the elevation of fetuin-B and hypertension, combined with the previous role of fetuin-B in CVDs, we consider that fetuin-B may contribute to high blood pressure by affecting the function and structure of blood vessels." (PMID 37811770, 2023). "The results showed that the best cutoff point of fetuin-B in predicting hypertension was 63.14 μg/mL (sensitivity of 77.4%, specificity of 63.3% (area under the curve (AUC) = 0.7738, 95% confidence interval (CI): 0.7276–0.8200, P < 0.001)." (PMID 37811770, 2023). "To further study the relationship between serum fetuin-B and hypertension, we developed a multiple linear regression model." (PMID 37811770, 2023). "Our study demonstrated that there was a difference in serum fetuin-B between patients with essential hypertension and healthy people." (PMID 37811770, 2023). "A receiver operating characteristic (ROC) curve was used to evaluate the value of serum fetuin-B in diagnosing essential hypertension." (PMID 37811770, 2023). "Serum fetuin-B levels in patients with essential hypertension were significantly increased (76.65 ± 14.11 μg/mL vs 66.46 ± 15.51 μg/mL, P < 0.001)." (PMID 37811770, 2023). "Compared with healthy subjects, serum fetuin-B levels in patients with essential hypertension were significantly increased." (PMID 37811770, 2023). "Therefore, this study aims to further explore the correlation and mechanism between fetuin-B and hypertension." (PMID 37811770, 2023). "As fetuin-B is highly sensitive for detecting hypertension, it may have certain significance for the early intervention of hypertension, or it may become a new biomarker for clinical application." (PMID 37811770, 2023). "However, the reason for the increased serum fetuin-B in patients with essential hypertension is still unclear, and its specific mechanism still needs further study." (PMID 37811770, 2023). "Therefore, a large number of prospective studies are needed to determine the correlation between fetuin-B and essential hypertension." (PMID 37811770, 2023). "In this study, we discussed the relationship between fetuin-B and essential hypertension." (PMID 37811770, 2023). "However, to date, no study has evaluated whether the function of fetuin-B can induce hypertension, and the correlation between fetuin-B and hypertension remains unclear." (PMID 37811770, 2023). "Therefore, we speculated that fetuin-B might be involved in the occurrence and development of essential hypertension by regulating lipid metabolism." (PMID 37811770, 2023).
Hypertension (continued). "Although no information is available about the correlation between fetuin B and hypertension, increasing evidence suggests that alteration of its expression is associated with metabolic dysfunction and also cardiovascular disease." (PMID 36014793, 2022).
Abdominal obesity (3 papers, 2022 to 2025). Excessive fat around the stomach and abdomen. "A follow-up study among 1140 patients with abdominal obesity revealed that increased pulse wave conduction velocity was significantly related to a high prevalence of NAFLD and fetuin-B, which suggested that fetuin-B might be associated with subclinical atherosclerosis through fat accumulation." (PMID 37811770, 2023).
atherosclerosis (3 papers, 2022 to 2024). A disease characterized by the build-up of fatty material and calcium deposition in the arterial wall resulting in partial or complete occlusion of the arterial lumen. "Fetuin B, a peptide hormone linked with atherosclerosis and vascular plaque instability, is also increased in this demographic." (PMID 39634976, 2024). "These associations among fetuin-B, atherosclerosis, and cardiovascular diseases suggest the need for further work to clarify the role of fetuin-B in ISR." (PMID 35265678, 2022). "Data show that increased levels of fetuin B have been linked to T2DM, atherosclerosis, and risk for inflammation in vascular plaque, causing plaque instability." (PMID 39634976, 2024).
Infertility (3 papers, 2021 to 2023). "Fetuin-B was identified in mice as a plasma protein inhibiting ovastacin, a cortical granula protease known to cause ZP hardening and infertility." (PMID 34311720, 2021). "Consequently, in the absence of fetuin-B, ZP2 cleavage occurs prematurely and leads to infertility of female fetuin-B deficient mice." (PMID 34320465, 2021). "In light of the recent research associating a truncated variant of ASTL with infertility, and the observation of altered fertility in ASTL−/− and FETUB−/− female mice, we conducted an analysis of nsSNPs and regulatory SNPs in ASTL from the dbSNP database." (PMID 37363721, 2023). "Ablation of FETUB in female mice leads to infertility due to premature zona hardening of unfertilized oocytes." (PMID 37363721, 2023).
liver fibrosis (3 papers, 2019 to 2021). "Thus, the relationship between fetuin-B and liver fibrosis needs to be further studied." (PMID 32326594, 2020). "Although there may be a negative correlation between fetuin-B and liver fibrosis, this study did not consider exploring sources of heterogeneity with respect to liver fibrosis because the liver fibrosis scores of the patients varied considerably across the eligible studies." (PMID 32326594, 2020).
asthma (2 papers, 2020 to 2026). "CST1, CLC, FETUB and VSMT1 were upregulated in asthma and allergic diseases in nasal studies, which could reflect overrepresentation of allergic diseases in our non-TB control group." (PMID 41542684, 2026).
COVID-19 (2 papers, 2021 to 2023). A disease caused by infection with severe acute respiratory syndrome coronavirus 2. "In our serum proteomics data, the abundances of AHSG, FETUB, HRG, and KNG1 are found to be highly correlated in each of the sampled COVID-19 patients and are consistently higher in the survivors." (PMID 34226277, 2021). "Moreover, the plasma proteins HRG, FETUB, KNG1, LCAT, AHSG, and FN1 increase over time in abundance in the Munich cohort, thus suggesting their regulation during COVID-19 disease development." (PMID 34226277, 2021).
Hyperglycemia (2 papers, 2020 to 2021). An increased concentration of glucose in the blood. "In patients with MetS, elevated insulin levels led to an increase in serum fetuin-B levels, while hyperglycemia inhibited fetuin-B release." (PMID 34646426, 2021). "In contrast, our human studies demonstrated that hyperglycemia may lead to an increase in fetuin-B levels in healthy women but inhibit fetuin-B release in patients with MetS." (PMID 34646426, 2021). "Therefore, the increased Fetuin-B level during the OGTT was mainly due to hyperglycemia stimulating its secretion." (PMID 33061822, 2020).
prostate carcinoma (2 papers, 2023 to 2024). A carcinoma that arises from epithelial cells of the prostate gland. "It was found that overexpression of FETUB increases the apoptosis of prostate cancer cells, followed by the inhibition of their proliferation, migration, and invasion, and also slows the growth of tumours when compared to controls." (PMID 38650655, 2024). "In humans, FETUB levels were significantly higher in normal prostate cell lines compared to prostate cancer (PC) cells, and FETUB overexpression inhibited PC cell proliferation, migration, and invasion by inhibiting the PI3K/AKT signaling pathway and inducing apoptosis." (PMID 38136890, 2023).
breast carcinoma (1 paper, 2023). "Interestingly, FETUB expression in rats is induced by estrogen and may inhibit breast cancer development under estrogen influence." (PMID 38136890, 2023).
emphysema (1 paper, 2016). "For this reason, FETUB, a member of the cystatin superfamily, may play a role in the development of emphysema." (PMID 27443820, 2016).
heart failure (1 paper, 2022). Inability of the heart to pump blood at an adequate rate to meet tissue metabolic requirements. "Conventional treatment for heart failure could attenuate the changes in up- (CPN1, and C3) and down-regulated proteins (serum albumin precursor, albumin isoform X1, IGLC, and fetuin-B) in stage C CHF." (PMID 35203200, 2022).
Hyperoxaluria (1 paper, 2017). Increased excretion of oxalates in the urine. "Results of our present study show that OPN, MGP, Fetuin B, Fn1, CD 44, Clusterin, Bikunin/AMBP genes are upregulated during hyperoxaluria and further increased with crystal deposition." (PMID 29091707, 2017).
lung disease (1 paper, 2025). "In lung disease, Fetuin-B has emerged as a potential biomarker, with its levels progressively increasing in COPD patients and correlating negatively with lung function." (PMID 40948797, 2025).
pancreatic cancer (1 paper, 2023). "Although those diseases are associated with pancreatic cancer, the roles of fetuin-B in cancer are not conclusive." (PMID 37759310, 2023).
primary hypertension (1 paper, 2023). "A binary logistic regression analysis showed that fetuin-B was an independent risk factor for primary hypertension (odds ratio: 1.060, 95% CI: 1.034–1.086, P < 0.001)." (PMID 37811770, 2023). "Receiver operating characteristic curve analysis was used to evaluate the predictive value of fetuin-B for primary hypertension, and the optimal cutoff point was 83.14 μg/mL (sensitivity 77.4%, specificity 63.3%) (area under the curve) = 0.7738, 95% CI 0.7276–0.8200, P < 0.001)." (PMID 37811770, 2023).
pulmonary TB (1 paper, 2024). "FETUB, a cysteine protease inhibitor, emerged as a key biomarker for pulmonary TB, but little is known about its pathological role." (PMID 38512356, 2024). "Four proteins, FCGR3B, FETUB, GGH, and SERPIND1, were present at significantly higher levels in the serum of pulmonary TB patients than both HCs and ORI cases, thereby exhibiting a high degree of specificity for TB." (PMID 38512356, 2024).
thyroid (1 paper, 2022). "From our results, we suspect that the thyroid antibodies may decrease the concentration of fetuin-B in plasma and may also influence the level of fetuin-B in follicular fluid, finally affecting the success of fertilization." (PMID 35340679, 2022).
Thyroid autoimmunity (1 paper, 2022). "Thyroid autoimmunity played a critical role in low fertilization rate possibly by direct actions and influencing the level of fetuin-B in plasma." (PMID 35340679, 2022). "The objective of the study is to investigate the relationships between fetuin-B, thyroid autoimmunity (TAI), and pregnancy outcomes in women undergoing in vitro fertilization and embryo transfer (IVF-ET)." (PMID 35340679, 2022).
metabolic disease (6 papers, 2020 to 2025). A congenital disorder (due to inherited enzyme abnormality) or acquired (due to failure of a metabolically important organ) disorder resulting from an abnormal metabolic process. "Previous studies have suggested that Fetuin-B seems to be a secreted adipokine related to metabolic diseases." (PMID 33061822, 2020). "Nevertheless, our data, as well as that of others, suggest a potential clue between Fetuin-B and the development of metabolic disorder and IR." (PMID 33061822, 2020). "This further supported our hypothesis that fetuin-B may aggravate metabolic disorder and IR in MetS individuals by promoting oxidative stress." (PMID 34646426, 2021). "Previous studies on serum fetuin-B (fetuin-like protein IRL685) have investigated its association with T2DM; however, the reason for the variation in serum fetuin-B and its regulatory factors in metabolic disease remain unclear." (PMID 34646426, 2021). "Therefore, the measurement of Fetuin-B concentration in clinical research can be used as a simple biomarker for screening metabolic disorders and IR in PCOS women." (PMID 33061822, 2020). "Thus, it is of great interest to further explore the relationship between circulating Fetuin-B and metabolic disorders and IR and to address the exact pathophysiological mechanisms by which Fetuin-B is increased in metabolic diseases." (PMID 33061822, 2020). "Fetuin B may be one of many pathways that link metabolic disease with myocardial injury." (PMID 38500750, 2024). "It did not investigate the direct effect of metabolic disorders and IR on circulating Fetuin-B, nor did it dynamically observe the changes of circulating Fetuin-B levels with the increase of insulin sensitivity." (PMID 33061822, 2020). "To determine whether the upregulation of Fetuin B and leptin can persist during the progression of metabolic disorders by feeding the HFD for a longer period, we further measured body fat, FBG levels and serum leptin and Fetuin B levels in mice fed HFD or chow for 18 weeks." (PMID 35896788, 2022).
tumor (6 papers, 2020 to 2024). "Fetuin-B, a biomarker of COPD, and annexin A2, which is recognized as a multiple tumour marker, were coidentified in five out of six treated rats’ self-control samples on D3." (PMID 37753171, 2023).
cardiovascular disease (4 papers, 2022 to 2025). "Recently, more studies have focused on the relationship between fetuin-B and cardiovascular disease." (PMID 37811770, 2023). "The mechanism of the elevation of circulating fetuin-B in patients with cardiovascular disease is still unclear." (PMID 37811770, 2023). "Considering our previous research and interest in the relationship between lipids and cardiovascular diseases, we herein used ELISA to validate three differentially abundant proteins involved in cholesterol metabolism: fetuin-B, APOC3, and CETP." (PMID 35265678, 2022). "However, it is still controversial whether fetuin-B can be used as a biomarker of cardiovascular disease." (PMID 37811770, 2023).
cancer (2 papers, 2019 to 2023). A tumor composed of atypical neoplastic, often pleomorphic cells that invade other tissues. "Meprin inhibition, on the other hand, renders fetuin-B a potential key-player in proteolytic networks controlling angiogenesis, immune-defense, extracellular-matrix-assembly and general cell-signaling, with implications for inflammation, fibrosis, neurodegenerative disorders and cancer." (PMID 30679641, 2019).
infection (2 papers, 2019 to 2024). The state of being infected such as from the introduction of a foreign agent such as serum, vaccine, antigenic substance or organism. "Furthermore, fetuin B inhibits Meprin, which has been shown to modulate the immune system by processing and activating pro-inflammatory cytokines and chemokines that in turn induce the migration of leukocytes to sites of injury or infection." (PMID 39224219, 2024). "Similarly, levels of Transferrin, Afamin, Fetuin A (Alpha-2-HS Glycoprotein), Fetuin B and Transthyretin were reduced in both infection types, and no statistical difference was found between their levels." (PMID 30774579, 2019).
FETUB also shares sentences with these, for which no sentence is quoted: non-alcoholic fatty liver disease (4 papers); acute coronary syndrome (2); Alzheimer disease (2); chronic obstructive pulmonary disease (2); acute lymphoblastic leukaemia (1); allergic disease (1); allergic rhinitis (1); bacterial infections (1); bone disorder (1); colorectal cancer (1); endocrine disorders (1); endothelial dysfunction (1); focal segmental glomerulosclerosis (1); hyperlipidemia (1); liver dysfunction (1); lung adenocarcinoma (1); lung carcinoma (1); Pituitary adenoma (1); prediabetes (1); preeclampsia (1); secondary hypertension (1); stable angina (1).